SMO (smoothened, frizzled class receptor)
Diseases named in the same sentence as SMO in open-access papers (continued):
Sharing a sentence is not in itself a finding about the gene and the disease.
ameloblastoma (28 papers, 2017 to 2026). The most common odontogenic tumor, arising from the epithelial component of the embryonic tooth and usually affecting the molar-ramus region of the mandible or maxilla. "Mutations in the MAPK pathway, particularly the activating BRAF V600E mutation, and mutations in the SMO gene of the Sonic Hedgehog signaling pathway, are considered pivotal in the pathogenesis of ameloblastoma." (PMID 41595485, 2026). "ATO, an FDA-approved drug for acute promyelocytic leukemia, has shown the potential to inhibit the oncogenic effects of SMO mutations in ameloblastoma cells." (PMID 40699660, 2025). "Studies have reported that a significant proportion of maxillary ameloblastomas harbor SMO mutations, whereas mandibular tumors are more likely to harbor BRAF mutations." (PMID 40699660, 2025). "Maxillary ameloblastomas exhibit unique genetic mutations, such as SMO and RAS mutations, and require a more radical surgical treatment than mandibular ameloblastomas to reduce the recurrence rates." (PMID 39659305, 2024). "On the other hand, in Sweeney's traditional study, a correlation is demonstrated with the histological pattern of ameloblastomas, where most cases of follicular or desmoplastic ameloblastomas exhibited mutations in either SMO or BRAF genes." (PMID 38615253, 2024). "Advanced next-generation sequencing (NGS) analyses identified the high frequency of BRAF V600E and SMO L412F mutations in all types of ameloblastoma." (PMID 36378285, 2022). "SMO gene mutation or CD44 dysregulation can reportedly contribute to a higher recurrence of ameloblastoma." (PMID 36242034, 2022). "The first of these is the detection of a high incidence of BRAF V600E and SMO L412F mutations in ameloblastoma." (PMID 36127985, 2022). "More recently, SMO mutations were identified in 39% of 28 ameloblastoma samples, primarily from maxillary ameloblastoma that tended to recur early." (PMID 36010600, 2022). "Within the MAPK pathway, the BRAFV600E mutation is found in 57% of ameloblastomas, while within the SHH pathway, Smoothened (SMO) mutations have been identified in 24% of ameloblastomas." (PMID 36127985, 2022). "Among them, SMO mutations have been detected in between 13 and 39% of ameloblastomas, occurring in a mutually exclusive pattern with BRAF p.V600E." (PMID 35048058, 2021). "In a similar way, other somatic mutations have been reported in ameloblastoma, mainly affecting: SMO, other MAPK pathway-related genes such as KRAS, NRAS, HRAS, FGFR2 and in a lower frequency, PTEN and CTNNB1 among others." (PMID 35048068, 2021). "Advanced next generation sequencing (NGS) analyses identified high frequency of BRAF V600E and SMO L412F mutations in ameloblastoma." (PMID 32096304, 2020). "Our data confirm previous studies who found that BRAF and SMO are by far the most frequent oncogenic driver mutations in ameloblastomas." (PMID 29388014, 2018). "BRAFV600E-mutant ameloblastomas presented at a much earlier age (mean age 42 years) as compared to SMO-mutated ameloblastomas, which was the oldest patient subgroup (mean age 67 years, rho = 0.299; p = 0.019)." (PMID 29388014, 2018). "Peripheral type ameloblastomas revealed exclusively single somatic mutations in BRAF or SMO (rho − 0.224, p = 0.010)." (PMID 29388014, 2018). "Using this method, it was discovered that mutations in the SMO gene encoding smoothened protein was commoner in maxillary ameloblastomas, while BRAF V600E mutations were commoner in mandibular ameloblastomas." (PMID 28592923, 2017). "Disruption of the Mitogen-Activated Protein Kinase (MAPK) and Sonic Hedgehog (SHH) signaling pathways, most notably through activating mutations in the BRAF and SMO genes, which are discussed later, appears to play a central role in the pathogenesis and biological behavior of ameloblastoma." (PMID 41595485, 2026). "Mutations in SMO have been identified in approximately 10.6% to 39% of ameloblastoma cases." (PMID 40699660, 2025).
ameloblastoma (continued). "Additionally, single somatic mutations in NRAS and SMO have also been detected in one peripheral ameloblastoma sample each in a mutually exclusive manner with the BRAF mutation." (PMID 35048058, 2021). "It is notable that the presence of two or three gene mutations, including somatic mutations in KRAS, PIK3CA, PTEN, FGFR, CDKN2A, and CTNNB1 in the background of either BRAF or SMO mutation-positive ameloblastomas, exclusively occurred in solid/conventional tumors." (PMID 35048058, 2021). "Mutations in SMO were found in 8 of 57 ameloblastomas (14%)." (PMID 29388014, 2018). "Taken all together, we may speculate that ameloblastomas and craniopharyngiomas share similar tumorigenic pathways and SMO-mutated ameloblastomas may resemble a distinct subtype of craniopharyngiomas with special reference to maxillary location." (PMID 29388014, 2018). "However, somatic KRAS, PIK3CA, PTEN, FGFR, CDKN2A, and CTNNB1 co-occurred also in the background of either BRAF- or SMO-mutated ameloblastomas." (PMID 29388014, 2018). "Additionally, we reported EGFR mutations and the presence of other gene mutations, including somatic mutations in KRAS, PIK3CA, PTEN, FGFR, CDKN2A, and CTNNB1 on the background of either BRAF or SMO mutation-positive ameloblastomas, occurring exclusively in conventional AMs." (PMID 36378285, 2022). "In that study, mandibular ameloblastomas predominantly harbored BRAF p.V600E mutations, while maxillary counterparts often carried SMO alterations." (PMID 41364259, 2025). "Mutations identified in humans with ameloblastomas have affected genes of the MAPK pathway; specifically, BRAFV600E mutations are predominantly in mandibular ameloblastoma while SMO mutations are mostly found in maxillary tumors." (PMID 38638641, 2024). "Additional mutations identified in mandibular ameloblastomas included JAK P132T, SMO, SMARCB1, PIK3CA, and CTNNB1." (PMID 38021761, 2023). "Associations with other mutations, such as SMO and FGFR2, have also been reported in maxillary ameloblastomas." (PMID 38021761, 2023). "Remarkably, the unilocular to multilocular pattern rate was higher (1.3:1, 1.5:1, respectively) in the tumors with BRAF and multiple gene mutations, in contrast to SMO, NRAS, HRAS, and EGFR-mutated ameloblastomas (1:3, 1:2, respectively)." (PMID 29388014, 2018). "Additional studies showed gene expression profile differences between plexiform and follicular ameloblastomas, with follicular ameloblastomas expressing variants of BRAF, KMT2D, and ABL1, while plexiform ameloblastomas expressed variants of ALK, BRAF, KRAS, KMT2D, SMO, KMT2A, and BRCA2." (PMID 38607614, 2025). "Another genetic test that can be conducted is for the smoothened (SMO) gene, which may be present in 14% to 39% of ameloblastoma patients." (PMID 39398651, 2024). "In maxillary ameloblastomas, additional mutations included BRAF L597R, FGFR2, PIK3CA, and SMO." (PMID 38021761, 2023). "In contrast, for ameloblastoma developed in the maxilla, mutations of the protein Smoothened (SMO) of the Hedgehog pathway, a non-MAPK pathway, is involved." (PMID 36428683, 2022). "Interestingly, ameloblastomas with BRAFV600E mutations are predominantly (96%) located in the mandible and ameloblastomas with SMO mutations are predominantly found in the maxilla (85%)." (PMID 36127985, 2022). "Aside from the SMO mutations, APC mutations have been detected in 3/6 ameloblastomas, and CTNNB1, PIK3CA, SMARCB1, PTEN, CDKN2A mutations have been reported in a few cases and tend to occur in a non-mutually exclusive manner with BRAF p.V600E mutation and with each other." (PMID 35048058, 2021). "Although SMO mutations have been identified in ameloblastoma in previous reports, no SMO mutations were detected in our samples." (PMID 28658279, 2017). "Recent studies revealed that some ameloblastomas harbour BRAF and SMO mutations that may render them sensitive to new small molecule therapies." (PMID 27965463, 2017).
ameloblastoma (continued). "The anatomical site, histological type of the tumour, sex and age of the patient, as well as BRAF-V600E and SMO-L412F mutations known to be common in ameloblastoma, were found to be independent of the level of ncRNA detected here." (PMID 27965463, 2017). "More recent understanding of the biological factors shows that ameloblastomas arising from the mandible are likely to be associated with mutations in the MAPK pathway, with BRAFV600E mutations being the most common, while those arising from the maxilla tend to have SMO mutations." (PMID 38607614, 2025). "The tumor margins were clearly demarcated in all SMO-mutated cases (in good agreement with the absence of recurrence in these cases), whereas the highest rate of unclear tumor margins were observed in wild-type ameloblastomas." (PMID 29388014, 2018). "We also confirm highly significant phenotypic differences in these two types of ameloblastomas as BRAF-mutant cases occurred preferentially in the mandible and at a much younger age (mean age 42 years) than SMO-mutant cases occurring preferentially in the maxilla at an older age (mean age 67 years)." (PMID 29388014, 2018). "Cortical expansion was prominent in ameloblastomas with BRAF or multiple gene mutations, but SMO-mutated tumors never revealed cortical expansion (p = 0.028)." (PMID 29388014, 2018).
colon carcinoma (28 papers, 2010 to 2024). "SMO activation in an abnormal way causes progression in colon cancer, and its expression was sharply upregulated in colon cancer tissues as compared to the non-cancerous colon tissues." (PMID 33489917, 2020). "Together with the role of functional SMO in regulating GLI3 activity, it suggests an SMO-dependent GLI signaling in colon cancer tumorigenesis." (PMID 34572373, 2021). "SMO inhibitor GDC-0449 suppresses colon cancer cells proliferation and triggers apoptosis via the downregulation of Bcl-2." (PMID 32962123, 2020). "Despite these controversies, most investigators agree that SMO is a potential target for colon cancer treatment." (PMID 32962123, 2020). "The role of SMO has been discussed in different types of cancer, including breast, liver, pancreatic and colon cancers." (PMID 32962123, 2020). "The efficacy of SMO inhibitors for treatment of malignancies of the breast, liver, pancreas and colon cancer has been demonstrated or is under clinical trials." (PMID 32962123, 2020). "It has been reported that Hh signaling is blocked more efficiently by GANT61 at the level of GLI1/GLI2, which in turn induces DNA damage and cell death in human colon carcinoma cells, compared with the SMO inhibitor cyclopamine." (PMID 27349387, 2016). "Other studies reported that GANT-61 inhibits GLI1/GLI2 in colon cancer cells that are resistant to the SMO inhibitors cyclopamine and GDC-0449; this observation suggests SMO-independent Hh signaling pathway activation in colon cancer." (PMID 26843616, 2016). "In contrast we have demonstrated minimal effects on GLI targets in human colon carcinoma cells in response to physiologically relevant concentrations of SMO inhibitors." (PMID 24962990, 2014). "We have previously reported that the GLI transcription factors are activated in a SMO-independent manner via oncogenic pathways such as RAS/RAF signaling axis in human colon cancer cells that are hence more sensitive to inhibition of GLI instead of SMO." (PMID 24086482, 2013). "In case of Colon cancer scenario, we found that inhibition of SMO, HFU, ULK3 and RAS was useful to suppress the expressions of various responsive proteins of Hedgehog pathway." (PMID 23935937, 2013). "We have demonstrated the importance of targeting GLI downstream of SMO in the induction of cell death in human colon carcinoma cells." (PMID 23097684, 2012). "Using GANT61, cyclopamine and GDC-0449 we have demonstrated the importance of targeting GLI downstream of SMO in termination of HH survival signaling that leads to the induction of cell death in human colon carcinoma cells." (PMID 23097684, 2012). "GANT61, and the classic SMO inhibitor cyclopamine (for comparison with other model systems), were evaluated in a panel of human colon carcinoma cell lines to determine the impact of inhibiting GLI1/GLI2 vs SMO." (PMID 21860067, 2011). "Collectively, the data demonstrate increased sensitivity of human colon cancer cells to inhibition of GLI genes compared to that of SMO." (PMID 21860067, 2011). "Thus, it can be targeted by SMO inhibitors which are investigated for treatment of breast, liver, and colon cancer." (PMID 37202799, 2023). "SMO affects colon cancer progression and can act as a biomarker for liver metastasis." (PMID 32962123, 2020). "The mutations of the SMO protein (A324T, V404M and T640A) in colon cancer produced no aberrant HH signaling activity." (PMID 32962123, 2020). "For example, Ding Y. and his colleagues revealed that SMO was highly expressed in colon cancer, which could be a potential biomarker of colon cancer." (PMID 31895689, 2019). "Moreover, the expression levels of PTCH and SMO were gradually increased as the colon cancer progressed from a benign to more malignant tumor." (PMID 30423843, 2018). "Furthermore, protein expression of SMO, Gli1, CD44, and CD133 was decreased in colon cancer cells in response to treatment with the SMO inhibitor cyclopamine." (PMID 27894099, 2016).
colon carcinoma (continued). "Thus, canonical activation of GLI1 and GLI2 via SMO is important for the survival and proliferation of human colon carcinoma cells in vivo." (PMID 20957031, 2010). "Similarly, SMO plays an important role in colon cancer progression." (PMID 31979397, 2020). "The results presented in this study indicated that the anticancer effect of celecoxib is selective in colon cancer cells; celecoxib may target cancer cells via the SMO-independent modulation of GLI1 activity, and Hh signaling may be significant in maintaining the malignant state of LoVo cells." (PMID 25295109, 2014). "Previous study showed that cyclopamine treatment results in decreased levels of mRNA coding for HH, SMO and PTCH, all of which were highly expressed in colon cancer cell lines." (PMID 34490089, 2021). "Therefore, SMO could be a potential treatment target for colon cancer." (PMID 32962123, 2020). "Cyclopamine treatment resulted in the inhibition of Hh, SMO, and PTCH mRNA, which were highly expressed in the colon cancer cell lines." (PMID 30423843, 2018). "When the Hh pathway was inhibited in HT29 cells with the SMO inhibitor cyclopamine, reduced expression of stemness markers, such as CD44 and CD133, was observed, suggesting that Prdx2 may promote CSC-associated properties in colon cancer via the Hh/Gli1 signaling pathway." (PMID 27894099, 2016). "On the other hand, our analysis also revealed that suppression of SMO, HFU and ULK3 by external drug would be required to completely shut down the Hedgehog signaling in the colon cancer cell line." (PMID 23935937, 2013). "Therefore, we propose that in order to shut down the effect of Hedgehog signaling in colon cancer cell line for in-vitro or in-vivo analysis, one could also think a combination of drugs that will suppress the activity of SMO, HFU, ULK3 and RAS proteins altogether." (PMID 23935937, 2013). "In colon cancer cells, BFT rapidly induced SMO gene expression, resulting in a 2- to 4-fold increase after 3 or 6 h of exposure, respectively, resulting in the production of SMO-dependent ROS and dysregulation of Gamma-H2AX, which further leads to DNA damage and induces carcinogenesis." (PMID 37553473, 2023). "In colon cancer, HDAC3 knockdown can suppress β-catenin translocation from the plasma membrane to the nucleus and increase the expression of Wnt inhibitors TLE1, TLE4 and SMO." (PMID 34991620, 2022). "Increased SMO expression was found in colon cancer tissues compared to normal tissues via immunohistochemistry staining." (PMID 32962123, 2020). "In this study, SMO and GLI3 were undetectable in the HT29 colon cancer cell line." (PMID 32784501, 2020). "In our study, Prdx2, SMO, Gli1, and CD133 expression was verified in the colon cancer cell lines." (PMID 27894099, 2016). "For example, inhibition of GLI, but not SMO, inhibited tumor growth in myeloid leukemia, colon carcinoma, hepatocellular carcinoma, and osteosarcoma." (PMID 23861973, 2013). "Of importance is the demonstration that targeting of SMO (using cyclopamine) has minimal effect on cell survival in comparison to the inhibition of GLI (using GANT61), which induced extensive cell death in 7/7 human colon carcinoma cell lines." (PMID 21860067, 2011). "We have demonstrated in human colon carcinoma cells that the GLI genes, the transcriptional regulators of the HH signaling response, are activated by both canonical signaling (via SMO) and by non-canonical activation (via the RAS/RAF pathway), which is activated in high frequency in colon cancers." (PMID 21860067, 2011).